METTL1 (methyltransferase 1, tRNA methylguanosine)
Diseases named in the same sentence as METTL1 in open-access papers (continued):
Sharing a sentence is not in itself a finding about the gene and the disease.
hepatocellular carcinoma (45 papers, 2020 to 2025). A malignant tumor that arises from hepatocytes. "METTL1 has been identified as a high-risk gene in hepatocellular carcinoma (LIHC), contributing to tumor-associated phenotypes by inhibiting PTEN signaling." (PMID 37396662, 2023). "As an important regulator of m7G, METTL1 expression is significantly upregulated in hepatocellular carcinoma and is associated with poor patient prognosis." (PMID 35847903, 2022). "Similarly, the enhancement of EGFR and VEGFA translation in lenvatinib‐resistant hepatocellular cancer has been linked to METTL1 activity." (PMID 39979979, 2025). "In hepatocellular carcinoma, METTL1 expression has been associated with PTEN signalling." (PMID 37516825, 2023). "In addition, METTL1 overexpression has been shown to be associated with poor prognosis and downregulation of tumor suppressors in hepatocellular carcinoma." (PMID 35865472, 2022). "METTL1 is increased in both RNA and protein levels in hepatocellular carcinoma, and acts as an oncogene." (PMID 38967523, 2024). "Above all, our data revealed that METTL1-meditated circIPP2A2 promoted malignant behaviors in hepatocellular carcinoma by serving as a scaffold in modulating the Hornerin/PI3K/AKT/GSK3β axis." (PMID 39616161, 2024). "Strategies such as TGF‐β signalling blockade, knockdown of hepatoma‐intrinsic Mettl1 or Tgfb2, or interruption of the METTL1‐TGF‐β2‐PMN‐MDSC axis can mitigate tumour progression induced by iRFA and restore the CD8+ T cell population." (PMID 38943267, 2024). "METTL1-mediated m7G tRNA modification enhances lenvatinib resistance in hepatocellular carcinoma (HCC)." (PMID 38425244, 2024). "In hepatocellular carcinoma, the METTL1/WDR4 complex promoted the translation of EGFR pathway genes via modulating m7G tRNA modification, which decreased the tumor’s susceptibility to Lenvatinib." (PMID 37710294, 2023). "Some groups found that METTL1 is tumor-promoting in colon cancer, hepatocellular carcinoma, and head and neck squamous cell carcinoma; additionally, opposite findings have also been reported." (PMID 35986847, 2022). "METTL1 exhibits oncogenic activity in hepatocellular carcinoma, while in colorectal cancer, it acts as a tumour suppressor." (PMID 35847903, 2022). "For example, METTL1 exerts oncogenic activity via suppression of PTEN signaling in hepatocellular carcinoma and via the AKT/mTORC1 pathway in lung adenocarcinoma." (PMID 36071474, 2022). "The expression levels of METTL1 and WDR4 are elevated in hepatocellular carcinoma (HCC) and are associated with advanced tumor stage and poor patient survival." (PMID 36333719, 2022). "METTL1 promoted the proliferation and migration of hepatocellular carcinoma cells by inhibiting the PTEN signaling pathway and was associated with poor prognosis." (PMID 34163522, 2021). "On the other hand, Tian QH found that METTL1 facilitated cell proliferation and migration and was correlated with poor prognosis of hepatocellular carcinoma." (PMID 33589575, 2021). "Overexpression of METTL1 in hepatocellular carcinoma has been shown to promote cell proliferation and migration, and to lead to poor prognosis in HCC." (PMID 32241281, 2020). "In some cancers (e.g., ICC, hepatocellular carcinoma), combining METTL1 inhibitors with ICIs may have synergistic effects." (PMID 41562049, 2025). "In addition, in hepatocellular carcinoma, METTL1-mediated modification of tRNA m7G boosts target mRNA translation with an increased frequency of m7G-related codons." (PMID 37238181, 2023). "For example, METTL1 has been shown to act as an oncogene in bladder cancer, hepatocellular carcinoma (HCC), acute myeloid leukemia, and intrahepatic cholangiocarcinoma; the METTL3/14 complex acts as a tumor suppressor in thyroid and endometrial cancers." (PMID 36830565, 2023). "The m7G tRNA modification and the expression of its methyltransferase complex components (METTL1 and WDR4) were significantly elevated in hepatocellular carcinoma (HCC)." (PMID 39723662, 2025).
hepatocellular carcinoma (continued). "In hepatocellular carcinoma (HCC), METTL1 knockdown suppresses the translation of cyclin A2, leading to the G2/M cell cycle arrest." (PMID 39979979, 2025). "In hepatocellular carcinoma, METTL1/WDR4-mediated m7G tRNA modification significantly promotes the translation of cyclin A2, EGFR, and VEGFA, promoting the spread and metastasis of hepatocellular carcinoma cells." (PMID 39019857, 2024). "It was shown that m7G tRNA modification and its methyltransferases METTL1, WDR4 and WBSCR22 were significantly elevated in HCC and promoted the proliferation, migration and invasion of hepatocellular carcinoma cells." (PMID 37710294, 2023). "METTL1 and WDR4 are upregulated in hepatocellular carcinoma (HCC) and intrahepatic cholangiocarcinoma (ICC), related with poor prognosis." (PMID 36092891, 2022). "METTL1, writer of the common 5'-cap modification m7G in mRNA and internal modification in other non-coding RNAs, is found upregulated in hepatocellular carcinoma (HCC)." (PMID 32194861, 2020). "In addition to the essential role of METTL1 in embryonic stem cell self-renewal and differentiation, it is elevated in hepatocellular carcinoma (HCC) and shows carcinogenic activity through PTEN/AKT signaling pathway." (PMID 32373523, 2020). "It has been shown that the oncogenic function of METTLl can promote tumor cell proliferation and migration by inhibiting the PTEN-related signaling pathway, and that inhibition of METTL1/WDR4 activity reduces m7G tRNA modification and slows down the progression of hepatocellular carcinoma." (PMID 40443650, 2025). "Previous reports have shown that METTL1 promotes esophageal squamous cell carcinoma through the RPTOR/ULK1/autophagy axis and mediates m7G tRNA modification to promote lenvatinib resistance in hepatocellular carcinoma." (PMID 38822363, 2024). "Furthermore, METTL1 can also promote the progression of HCC through the downregulation of PTEN pathway activity, suggesting that METTL1 could play a regulatory role in the development of hepatocellular carcinoma through multiple pathways." (PMID 37710294, 2023). "Although the implications of METTL1 in hepatoblastoma carcinogenesis have not been reported, two new publications showed that METTL1 is related to radiotherapy resistance and recurrence post-radiofrequency ablation in hepatocellular carcinoma." (PMID 35986847, 2022). "In our research we also found that METTL1 and WDR4 expression was upregulated in hepatocellular carcinoma tissues and correlated with reduced survival time, and also found that high METTL1 and WDR4 expression was distinctively and negatively relevant with the level of NK cell infiltration." (PMID 36389726, 2022). "Moreover, METTL1 overexpression promoted the proliferation and migration of hepatocellular carcinoma via the phosphatase and tensin homolog deleted on chromosome ten (PTEN) signalling pathway, suggesting that METTL1's function may vary between different tumour types." (PMID 34936728, 2021). "However, there is no doubt that METTL1, WDR4 and WBSCR22 are potential targets for the future treatment of hepatocellular carcinoma." (PMID 37710294, 2023).
intrahepatic cholangiocarcinoma (27 papers, 2021 to 2025). A carcinoma that arises from the intrahepatic bile duct epithelium in any site of the intrahepatic biliary tree. "Conversely, the disruption of m7G modification resulting from METTL1 knockout leads to global translation defects of oncogenes and the loss of typical malignant transformation markers, thereby inhibiting the occurrence and development of intrahepatic cholangiocarcinoma." (PMID 37654606, 2023). "METTL1-mediated m7G tRNA modification selectively promotes oncogenic mRNA translation via codon-frequency-dependent mechanisms to drive intrahepatic cholangiocarcinoma (ICC) progression." (PMID 40809384, 2025). "CXCL8 in human and Cxcl5 in mouse are key translational targets of METTL1 that facilitate its function in promoting PMN-MDSC accumulation in tumor immune microenvironment of intrahepatic cholangiocarcinoma." (PMID 40443650, 2025). "In intrahepatic cholangiocarcinoma (ICC), there is a significant METTL1/WDR4 upregulation, which is strongly linked to poor prognosis." (PMID 38943267, 2024). "Additionally, a study identifies METTL1 and m7G tRNA modification as selective regulators of mRNA translation, particularly impacting CDKs in intrahepatic cholangiocarcinoma." (PMID 38822363, 2024). "In line with our observations, recent studies have shown that METTL1 is involved in mediating the mRNA translation of cytokines that induce the accumulation of myeloid-derived suppressor cells (MDSCs) in intrahepatic cholangiocarcinoma, a major immune suppressive subset infiltrating these tumours." (PMID 37516825, 2023). "In a preclinical mouse model of intrahepatic cholangiocarcinoma (ICC), PD-1 treatment simultaneously blocked METTL1 and its downstream chemokine pathway (CXCL8 in the human body and CXCL5 in the mouse body), boosting the immune response in the mice." (PMID 39155349, 2024). "In intrahepatic cholangiocarcinoma (ICC), co-repressing METTL1 and its downstream chemokine pathway inhibited recruitment of myeloid-derived suppressor cells (MDSCs) and improved anti-PD-1 efficacy." (PMID 37612540, 2023). "Dai demonstrates the critical function of METTL1-mediated m7G tRNA modification in promoting ICC intrahepatic cholangiocarcinoma in vivo." (PMID 35620469, 2022). "In vitro and in vivo, the EGFR pathway genes and the genes involved in cell-cycle were scrupulously regulated by METTL1-mediated m7G tRNA modification and thus promoted intrahepatic cholangiocarcinoma (ICC) progression." (PMID 36118897, 2022). "In advanced intrahepatic cholangiocarcinoma (ICC), polymorphonuclear MDSCs (PMN-MDSCs) are significantly enriched and correlated with METTL1 expression." (PMID 40176140, 2025). "Liu et.al recently revealed that METTL1-mediated m7G modification significantly regulates PMN-MDSCs accumulation in the immune microenvironment and intrahepatic cholangiocarcinoma progression through targeting CXCL8 in humans and Cxcl5 in mice." (PMID 39440054, 2024). "A higher m7G tRNA modification level, as well as the upregulated expression of METTL1 and WDR4, two m7G methyltransferases, were observed in intrahepatic cholangiocarcinoma (ICC) compared to adjacent normal tissues." (PMID 36009465, 2022). "Similarly, in intrahepatic cholangiocarcinoma (ICC), METTL1‐ driven m7G tRNA modification drives the translational efficiency of oncogenic transcripts, including EGFR signalling pathways and cell cycle genes, thereby contributing to cancer progression." (PMID 41208200, 2025). "Moreover, METTL1 upregulates the expression of chemokines CXCL5 and CXCL8 in an m7A-dependent manner, leading to MDSCs accumulation and immunosuppression in HCC and intrahepatic cholangiocarcinoma (ICC)." (PMID 38902779, 2024). "The METTL1/WDR4‐mediated m7G modification in tRNA plays a pivotal role in various digestive system neoplasms, including HCC, oesophageal squamous cell carcinoma (ESCC), gastric cancer (GC), intrahepatic cholangiocarcinoma (ICC)." (PMID 38943267, 2024).
colon cancer (23 papers, 2019 to 2025). "Similar findings were found in colon cancer, in which METTL1 overexpression inhibited proliferation and migration of CC cells." (PMID 41208200, 2025). "To explore the biological functions of METTL1 in the progression of colon cancer, we overexpressed and inhibited the expression of METTL1 in HCT116 and RKO cell lines." (PMID 37692515, 2024). "Taken together, these findings indicated that METTL1 promoted colon cancer cell proliferation both in vitro and in vivo." (PMID 37692515, 2024). "Zhang and Cui found that METTL1 promotes the proliferation of colon cancer cells through stabilizing CDK4 via m7G modification." (PMID 38967523, 2024). "Global gene expressions of siMETTL1-1, siMETTL1-2, and siNC cells were sequenced to explore the mechanism of METTL1 on colon cancer development." (PMID 37692515, 2024). "Another study found that overexpression of METTL1 increases the sensitivity of colon cancer cells to cisplatin." (PMID 38822363, 2024). "METTL1 was downregulated in cisplatin-resistant colon cancer cells compared to their paired cisplatin-sensitive colon cancer cells." (PMID 37612540, 2023). "Methyltransferase-like 1 (METTL1)-mediated m7G regulates the progression and chemosensitivity of colon cancer." (PMID 36185235, 2022). "Overexpression of METTL1 suppresses colon cancer (CC) cells proliferation, invasion, migration, and induces cell apoptosis in a m7G dependent manner." (PMID 36118897, 2022). "The results of our study are similar to those of other studies that have shown that METTL1 also promotes tumor proliferation in liver and colon cancers." (PMID 34838021, 2021). "Similarly, METTL1 regulates the let‐7e miRNA/HMGA2 axis through m7G methylation modification to inhibit colon cancer (CC) progression." (PMID 41208200, 2025). "In contrast, METTL1 is considered a latent tumor suppressor of colon cancer." (PMID 36118897, 2022). "Interestingly, methyltransferase METTL1 served as a tumor suppressor and conferred chemosensitivity to cisplatin in colon cancer." (PMID 33589575, 2021). "However, the role of METTL1 in regulating chemoresistance of colon cancer (CC) cells to cisplatin is still unclear." (PMID 31866582, 2019). "However, further experiments are still needed to explore whether METTL1 regulated miR-149-3p levels in colon cancer in a m7G dependent manner." (PMID 31866582, 2019). "We further assess the effect of METTL1 and WDR4 on the immune microenvironment in colon cancer by ssGSEA algorithm." (PMID 39440054, 2024). "We also assessed the effect of METTL1 and WDR4 on the immune microenvironment in colon cancer." (PMID 39440054, 2024).
bladder cancer (21 papers, 2021 to 2025). "In the context of bladder cancer, METTL1 is involved in m7G modification of miR-760, leading to the suppression of ATF3 mRNA expression." (PMID 40809690, 2025). "In the context of bladder cancer, METTL1 has been shown to promote proliferation, invasion, and migration by modifying tRNAs in an m7G-dependent manner, which enhances the translational efficiency of EGFR/EFEMP1 and TROP2." (PMID 40809690, 2025). "METTL1-mediated m7G hypomethylation promotes tsRNA biogenesis in prostate cancer, and m7G-modified tsRNA-LysTTT catalyzed by METTL1 enhances bladder cancer malignancy." (PMID 40565315, 2025). "METTL1 can affect the m7G tRNA-mediated codon-specific translation of EGFR/EFEMP1 by regulating tRNA m7G modification to regulate bladder cancer cell behavior." (PMID 40360483, 2025). "Silencing METTL1 suppresses the migration and invasion of bladder cancer cells in vitro and in vivo." (PMID 39289775, 2024). "METTL1 was highly expressed in bladder cancer, and its level was correlated with poor patient prognosis." (PMID 39289775, 2024). "For example, EFEMP1 protein expression was upregulated by METTL1-mediated m7G tRNA modification, which in turn leads to bladder cancer development." (PMID 36973645, 2023). "METTL1 and WDR4 are complex catalyst of m1A modification, and METTL1 overexpression in bladder cancer is linked to a poor prognosis and mediates m7G tRNA modification." (PMID 37194218, 2023). "In the urinary system, a study had shown that METTL1 is highly expressed in bladder cancer patients, and its expression level is positively correlated with the poor prognosis of patients." (PMID 36003341, 2022). "We found that the downregulation of METTL1 led to decreased m7G level and overexpression of METTL1 led to increased m7G level showing that METTL1 was exactly a m7G writer in bladder cancer." (PMID 36396627, 2022). "By contrast, the biological functions of methyltransferase‐like 1 (METTL1)‐regulated m7G tRNA modification in bladder cancer (BC) remain obscure." (PMID 34936728, 2021). "For example, METTL1 is associated with poor prognosis in bladder cancer, and it regulates the translation of EGFR/EFEMP1 by modifying certain tRNAs to inhibit the proliferation, migration and invasion of bladder cancer cells." (PMID 40443650, 2025). "m7G-modified tsRNA-LysTTT catalyzed by METTL1 enhances bladder cancer malignancy." (PMID 40565315, 2025). "Moreover, METTL1-mediated m7G-3′-tiRNA LysTTT promoted bladder cancer malignancy by binding to ANXA2 to enhance its phosphorylation by Yes1." (PMID 40045194, 2025). "METTL1, for example, can promote bladder cancer development." (PMID 36482181, 2022). "EGFR plays a crucial role in the METTL1-m7G axis in bladder cancer." (PMID 36468039, 2022). "However, the role of internal m7G at miRNAs and its core writer METTL1 in bladder cancer (BCa) remains to be elucidated." (PMID 36396627, 2022). "Furthermore, METTL1-m7G-EGFR/EFEMP1 axis is a precise mechanism for bladder cancer development." (PMID 36468039, 2022). "To investigate the effect of METTL1 on the acute stress response in urothelial cells, we utilized the normal uroepithelial SV-HUC-1 cells expressed the low METTL1, and the bladder cancer T24 cells, which exhibits the high expression level of METTL1." (PMID 40762925, 2025). "Furthermore, METTL1 can also modify miR-760 in an m7G-dependent manner to suppress ATF3 mRNA expression, thereby contributing to the progression of bladder cancer." (PMID 40809690, 2025). "With the expression level increasing, the poorer prognosis was observed, and the higher expression of METTL1 was observed in bladder cancer with metastasis group comparing to bladder cancer without metastasis group (P value: 2.022e-3)." (PMID 36396627, 2022).